MITF (melanocyte inducing transcription factor)
Diseases named in the same sentence as MITF in open-access papers (continued):
Sharing a sentence is not in itself a finding about the gene and the disease.
melanoma (continued). "However, the novelty of our study is to have attributed a peculiar role, in the evolution of targeted therapy resistance, to miR-579-3p whose oncosuppressive role in melanoma may be only in part related to MITF regulatory network." (PMID 38472212, 2024). "In addition to decreased melanoma antigen expression and presentation, melanoma cells with low MITF expression have been reported to develop an inflammatory secretome and display altered expression of the immune checkpoint protein programmed death ligand 1 (PD-L1)." (PMID 39736644, 2024). "We investigated the distinctive phenotype of these MITF−/low melanoma cells unveiling the loss of E-cadherin (CDH1) accompanied by concomitant increased expression of N-cadherin (CDH2), a feature associated with epithelial-to-mesenchymal transition (EMT) in various cancers including melanoma." (PMID 38191367, 2024). "Our observation of lower proportions of MITF+ melanoma cells in patients’ metastatic lesions taken after immunotherapy compared to pre-therapy supports the hypothesis of a more efficient targeting of these cells by therapy-induced immune response, while AXL+ melanoma cells may be more resistant." (PMID 39697983, 2024). "Consequently, AR promotes melanoma metastasis, a process that could potentially be counteracted by restoring MITF expression." (PMID 39597836, 2024). "Indeed, the acid SMase elicits MAPK activation and proteasomal degradation of MITF in melanoma." (PMID 39136013, 2024). "Additionally, through transcriptome profiling of 11 melanoma cell lines, we found the presence of ATP1A1 in the Verfaillie proliferative gene signature, which is associated with the melanocytic state characterized by MITF and SOX10 expression." (PMID 38178183, 2024). "Similarly, variations in the efficiency of the MITF knockdown itself could also partly explain the varying results observed in our melanoma cell lines." (PMID 39736644, 2024). "In addition, we found associations between MITF targeting and PTPN20, a tyrosine phosphatase coding gene, providing further evidence that disrupted signaling mediated by MITF regulation plays an important role in melanoma." (PMID 36894939, 2023). "Increased genetic risk for melanoma can occur in the context of germline pathogenic variants in high-penetrance genes, such as CDKN2A and CDK4, risk variants in low- to moderate-penetrance genes (MC1R and MITF), and possibly due to variants in emerging genes, such as ACD, TERF2IP, and TERT." (PMID 37958811, 2023). "Also, we found that A-alum-1 was able to modestly suppress the α-MSH-induced mRNA expression of MITF and tyrosinase in human melanoma SK-mel-28 cells, similarly to that in B16F1 cells, suggesting that A-alum-1 can inhibit melanogenesis through a transcriptional suppression-mediated mechanism." (PMID 37834109, 2023). "Furthermore, our findings may be particularly relevant to IFNγ-rich tumors and MITF-expressing melanomas." (PMID 36812891, 2023). "Furthermore, it was found that FB-ChiBai significantly attenuated melanin production, tyrosinase activities, and melanogenesis-related signaling pathways and reduced the nuclear translocation and promoter binding activities of MITF in B16F0 murine melanoma cells." (PMID 38140115, 2023). "Immunoprecipitation of MITF from an IGR37 human melanoma cell line engineered to express inducible p300 and HA-MITF so as to partially maintain their relative expression levels revealed an increase in acetyl K206 MITF after induction using doxycycline, confirming a role for p300 in MITF acetylation." (PMID 37770430, 2023). "One of the possible explanations for discrepancies in response to alternating periods of trametinib withdrawal and rechallenge between investigated trametinib-resistant cell lines could be the level and activity of MITF, a main regulator of phenotype in melanoma." (PMID 37175614, 2023).
melanoma (continued). "Furthermore, imperfections in Rec in proliferative melanoma cells could reduce production of MITF mRNA and over-expression of EMT, which both can impose invasibility on proliferative melanoma cells." (PMID 37112663, 2023). "Among the signals from the 13 melanoma essential TFs, the ChIP-seq results suggested that the classical melanoma driver TF, MITF, might not be associated with these enhancers." (PMID 37904237, 2023). "Therefore, we hypothesized that the reason for α-Mangostin to down-regulate only the expression of MITF in M14 cells might be related to the different basic expression of MITF among these four types of melanoma cells, which requires further investigation." (PMID 37575275, 2023). "Thus, while MITF mRNA levels might contribute to controlling the immune response to melanoma, other factors, for example MITF post‐translational modifications or expression of MITF cofactors, must also be important." (PMID 35771179, 2022). "Therefore, the MITF-SCD axis seems to play an important role in regulating melanoma plasticity." (PMID 35406721, 2022). "Moreover, a low transcriptional activity of MITF would predict poor outcomes for melanoma patients." (PMID 35631574, 2022). "To this end, we used RNA‐seq data from the 473 sample TCGA melanoma cohort to identify differentially expressed genes (DEGs) with an adjusted p‐value (q‐value) ≤ 0.05 whose expression was significantly different between the top and bottom 25% when ranked by MITF expression." (PMID 35771179, 2022). "Moreover, in vivo, expression of MITF in melanoma anticorrelates with immune infiltration." (PMID 35771179, 2022). "Indeed, the role of PARP1 in melanoma is dependent on MITF signaling." (PMID 35562405, 2022). "However, given that different melanoma cell lines exhibit a highly variable gene expression response to activation of a specific transcription factor, it was unlikely that the common genes include the full repertoire MITF targets." (PMID 35771179, 2022). "Furthermore, it is reported that an MITF-dependent melanoma patient-derived cell line, 501Mel, showed induction of RagD expression and increased mTORC1 activation, and the silencing of RagD was sufficient to greatly revert the hyperproliferative phenotype of this melanoma cell line." (PMID 35563798, 2022). "However, since MITF is considered as an undruggable target, targeting pathways that regulate its expression or activity could be more effective in melanoma therapy." (PMID 36499416, 2022). "Furthermore, the experimental depletion of HERV-K Rec in melanoma led to a lower level of melanocyte-inducing transcription factor (MITF), which may impact the transition from proliferative to invasive stages of melanoma." (PMID 35719395, 2022). "MITF phosphorylation is short term and happens immediately after allergic trigger, since longer exposure time may lead to ubiquitin-mediated degradation, as was observed in previous studies in melanoma." (PMID 35159398, 2022). "However, there are also genome-wide copy number alterations in melanoma: amplification affects the melanoma oncogenes, as well as CCND1 (cyclin D1) and MITF, while loss of heterozygosity (LOH) or complete loss may affect CDKN2A (p16) and PTEN." (PMID 35628196, 2022). "Interestingly, SMILE was significantly downregulated in melanoma tissues (p = 0.0003) compared to normal tissues, whereas the expression of the melanocyte-specific form of MITF (MITF-M) and its melanogenic target genes such as TYR and TRP1 was upregulated as expected." (PMID 36499416, 2022). "Finally, whether the synergistic effect of Wnt inhibition/MITF inhibition and anti-PD-1 antibodies on melanoma advancement was dependent on ferroptosis was also examined in vivo." (PMID 36429010, 2022).
melanoma (continued). "In metastatic melanoma cell lines and tumors, MITF positively correlated with the expression of lysosomal and autophagosomal genes, and the knockdown of MITF resulted in starvation-induced autophagy degradation in both melanocytes and melanoma cells, presumably due to less autophagosomal formation." (PMID 35563798, 2022). "Thus, down‐regulation of NRF2 not only induces CD44, but maybe also MITF, and both markers confer anti‐cytotoxic abilities to melanoma cells." (PMID 34951143, 2022). "Indeed, MITF functions as a rheostat that dictates the phenotype of melanoma cells." (PMID 35406721, 2022). "Microphthalmia-associated transcription factor (MITF) acts as a master regulator of melanocyte function, development and survival by modulating various differentiation-related, cell cycle progression-related and antiapoptotic genes and can act as an oncogene in melanoma 14-17." (PMID 33746605, 2021). "Furthermore, high MITF expression in melanoma contributes to resistance towards MAPK inhibitors." (PMID 33418925, 2021). "The identification of ADAM10 as an MITF target gene, suggests that MITF may play a dual role in shaping the anti-melanoma immune response, both promoting expression of antigens like MLANA known to elicit a robust T-cell response, but at the same time suppressing NK-cell-mediated killing." (PMID 33789714, 2021). "Interestingly, about 50% of relapsed melanoma express reduced levels of MITF." (PMID 34071193, 2021). "Structurally, MITF encodes a basic–helix–loop–helix leucine zipper (bHLH-ZIP) transcription factor, thereby exerting its function by regulating genes involved in cell cycle progression and differentiation, a role sustained throughout the process of melanogenesis and in melanoma." (PMID 34356645, 2021). "Moreover, we show that RNF43 could be a negative regulator of melanoma phenotype plasticity by targeting MITF-low/WNT5A-high melanoma cells." (PMID 34702444, 2021). "Hence, targeting MITF in combination with BRAF or cyclin-dependent kinase may offer a rational therapeutic way on melanoma." (PMID 34289891, 2021). "Importantly, we found that cell survival of MITF- KO cells might be dependent on FAK pathway; therefore, this might be the therapeutic vulnerability of MITF-low melanoma cells and can potentially enhance the current treatment options of melanoma." (PMID 33438577, 2021). "However, given the association of hereditary predisposition syndromes in patients with melanoma and/or mesothelioma with renal neoplasia, universal screening may be warranted in this patient population with a panel that includes BAP1, MITF, and FLCN." (PMID 34767027, 2021). "We found that although TNFα signaling was intact in all melanoma cells, the response to TNFα was dependent on the differentiation status of melanoma cells, with the melanocytic and transitory melanomas showing more pronounced downregulation of the pigmentation regulator MITF." (PMID 34073253, 2021). "Overexpression of MITF is associated with a negative progression of melanoma disease." (PMID 33990669, 2021). "The central role of MITF in melanoma biology as well as in shaping the immune response means that approaches combining inhibition of ADAM10 with manipulation of MITF levels, for example to sensitize cells to therapy, may provide an avenue towards more effective immune therapy." (PMID 33789714, 2021). "However, whether MITF might control sensitivity of melanoma cells to the immune system remains unclear, and whether modulation of MITF levels using currently available therapeutic modalities might impact the immune response is unknown." (PMID 33789714, 2021). "Triple SOX10/SOX11/MITF positivity might serve as a diagnostic tool for conventional pan-melanoma cocktail negative cases." (PMID 33801642, 2021).
melanoma (continued). "The association between this variant and melanoma, renal cancer, as well as other malignancies, may be related to shared environmental or polygenic risk factors, rather than this specific MITF polymorphism." (PMID 34289891, 2021). "Taken together, our data show that in a subset of melanoma cultures (switchers), a high tyrosine level promotes a phenotype switch from a differentiated to an invasive/undifferentiated state (EMT-like state) associated with MITF repression, EMT-TF reprogramming and RTK induction." (PMID 34869032, 2021). "Therefore, one potential mechanism of increased dependency on FADS2-mediated fatty acid desaturation in MITFlow/AXLhigh LD-rich melanoma cell lines could be a compensatory mechanism due to reduced MITF-regulated SCD." (PMID 37849907, 2021). "To schematize, going from nevus to melanoma is necessary the loss of cyclin dependent kinase inhibitor 2A (CDKN2A) and phosphatase and tensin homologue (PTEN), together with the down-regulation of MITF master gene in the evolution from radial to vertical growth phase melanoma." (PMID 34207514, 2021). "Despite this advance, loss of microphthalmia-associated transcription factor (MITF), the gene regulating pigmentation, is reported in melanomas with an invasive phenotype, indicating an unmet need to identify new molecular markers for detecting aggressive and invasive melanoma." (PMID 37849907, 2021). "However, in melanoma, ZEB1 and ZEB2 function antagonistically and play a central role in “phenotype switching” by modulating the expression of microphthalmia-associated transcription factor (MITF), a master regulator of melanocyte homeostasis and differentiation." (PMID 34298815, 2021). "Other mutated genes found in melanomas belong to pathways fundamental for the progression of the metastatic disease, for instance mitogen-activated protein kinase (MAPK), phosphoinositide 3-kinase (PI3K), WNT, receptor tyrosine-protein kinase KIT and melanocyte inducing transcription factor (MITF)." (PMID 34830947, 2021). "In addition to its roles in suppressing NK cell-mediated killing and expression of melanoma antigens, MITF has an additional role in regulating the immune response by suppressing the expression of an inflammatory secretome that can lead to effects on immune cell attraction." (PMID 33789714, 2021). "The involvement of MITF in migration has mostly been characterized using knockdown studies in melanoma cell lines using either siRNA or shRNA and by using Matrigel-coated Boyden chambers; in these studies, knocking down MITF resulted in increased migration properties." (PMID 33438577, 2021). "Indeed, modulating MITF activity can alter the ability of melanoma cells to respond to therapy." (PMID 33789714, 2021). "In that case, inhibition of MITF might be deleterious in melanoma treatment." (PMID 33803640, 2021). "Early studies identified a role for the melanoma survival gene MITF as a mediator of non-mutational and reversible drug tolerance, which has been characterised by proliferative to invasive phenotype switching, altered mitochondrial metabolism, and adaptive starvation responses." (PMID 34830962, 2021). "TPC2 inhibition thus provides a twofold benefit in melanoma prevention and treatment by increasing, through interference with tyrosinase activity, the synthesis of UV blocking melanin in melanosomes and by decreasing MITF-driven melanoma progression by increased GSK3β-mediated MITF degradation." (PMID 33875769, 2021).
melanoma (continued). "One critical effect of TNFα is the induction of melanoma dedifferentiation, characterized by the downregulation of the melanocytic antigen Melan A (MLANA gene) and the microphthalmia-associated transcription factor MITF, and the upregulation of NGFR and the AXL receptor tyrosine kinase." (PMID 34073253, 2021). "The unspecific pattern was found more frequently in melanomas of MITF+ (45% of the lesions) than in those of MITF− patients (13% of the lesions), while the multicomponent pattern was seen more frequently among melanomas of MITF− (65% of the lesions) than those of MITF+ patients (22%)." (PMID 32054529, 2020). "Therefore, different expression of both, NGFR and MITF in melanoma cells might be responsible for diverse outcomes at the level of phenotype." (PMID 31936151, 2020). "In addition, collagen stiffening can promote melanoma differentiation via YAP/paired box 3 (PAX3)-mediated MITF expression, supporting the notion that collagen density and rigidity may also govern melanoma cell plasticity and intra-tumor heterogeneity." (PMID 32466585, 2020). "In particular, high levels of AXL in melanoma are associated with a transcriptional reprogramming that induces a switch from a proliferative to an invasive phenotype, intrinsically less sensitive to inhibition of the BRAF/MAPK pathway and characterized by low levels of MITF expression." (PMID 33291749, 2020). "Therefore, it has been strongly emphasized that these diverse effects of β-catenin in melanoma cells and epithelial-derived cancers may be connected with the activity of MITF." (PMID 32659938, 2020). "Therefore, MITF is considered to be a master regulator of ‘phenotype switching’ between proliferative and invasive states, contributing to the high plasticity of melanoma cells in response to changes in the tumor microenvironment, including response to treatment." (PMID 32659938, 2020). "It is worth noting that the regulation of KIT by MITF in melanocytes and melanoma cells remains to be clearly demonstrated, indicating that a tissue specific regulation of KIT by MITF in mast cells might be explained by expression of lineage-restricted cofactors." (PMID 33276788, 2020). "However, regarding the transcriptomic classification of melanomas, we found that G3 was enriched with metastatic melanoma samples classified into the MITF-low subclass whereas melanomas clustered into the Immune subclass were more present among G1 and G2 (Fisher’s exact test p = 2.51e−06)." (PMID 32024530, 2020). "Importantly, the SphK1/S1P pathway could also modulate MITF levels, probably by acting on signaling pathways known to regulate its expression in melanoma cells." (PMID 33121001, 2020). "Furthermore, hereditary melanoma has been associated with germline mutations in high-risk melanoma susceptibility genes (CDKN2A, CDK4, TERT, POT1), polymorphisms in intermediate-risk melanoma susceptibility genes (BAP1, ACD, TERF2IP, MC1R and MITF), and germline missense substitutions in MITF." (PMID 32276436, 2020). "Moreover, MITF plays an important pro-survival role in melanoma cells." (PMID 32659938, 2020). "However, the role of MITF in melanoma development and progression is equivocal." (PMID 32850759, 2020). "Moreover, we found that RANKL expression was up‐regulated at both RNA and protein level, in the melanoma CM‐differentiated osteoblasts, suggesting that it could contribute to the induction of MITF expression in melanoma cells." (PMID 31323160, 2020). "However, it is currently not known if a reduced expression of MITF is associated with LD accumulation in dedifferentiated melanoma cells." (PMID 33121001, 2020).